YAP1 (Yes1 associated transcriptional regulator)
Diseases named in the same sentence as YAP1 in open-access papers (continued):
Sharing a sentence is not in itself a finding about the gene and the disease.
colorectal cancer (continued). "Consistently, inhibition of H3K9me2 has been shown to remarkably stimulate YAP1 expression in colorectal cancer cells." (PMID 32092824, 2020). "In summary, our findings revealed that the ZEB1-AS1/miR-205/YAP1 axis plays an important role in colorectal cancer which provides potential molecular biomarkers and therapeutic targets in CRC." (PMID 32190742, 2020). "FSS exposed colorectal cancer cells showed Akt-mediated upregulation of atonal bHLH transcription factor 8 (ATOH8) and yes-associated protein 1 (YAP1), transcription factors that enhance cancer cell survival, growth, metastasis, and metabolic remodeling." (PMID 32708855, 2020). "Regarding drug resistance and the Hippo-YAP1 pathway, a previous study indicated that the Hippo-YAP1 pathway played a crucial role in 5FU resistance in colorectal cancer." (PMID 31543507, 2019). "In colorectal cancer, DDX3X expression has been detected, and positive associations between DDX3 and KRAS, YAP1, and SIX2 have been observed in KRAS wild-type patients." (PMID 31906196, 2019). "For an instance, a cell density sensitive miRNA named miR-590-5p was shown down-regulated in GC cells and its binding site at YAP1 3’UTR was identified in colorectal cancer." (PMID 30934860, 2019). "Several studies show that dysregulation of YAP1 is important in the development of colorectal cancers." (PMID 31216773, 2019). "Among 36 colorectal cancer specimens, up to 86% scored positively for YAP1 and β‐catenin expression." (PMID 28782275, 2018). "Increasing expression of YAP1 protein was detected in numerous cancers, including esophageal cancer, gastric cancer, and colorectal cancer." (PMID 30539010, 2018). "Elevated expression of YAP1 has been observed among cases in four databases of colorectal cancer patients." (PMID 28782275, 2018). "Consistently, an elevated YAP1 immunostaining was detected in the paraffin-fixed sections from a small cohort of colorectal cancer patients." (PMID 28241877, 2017). "Positive correlation among YAP1 and Ascl2 mRNA levels was observed in colorectal cancer (CRC) samples." (PMID 29312609, 2017). "Yes-associated protein 1 (YAP1) is a well-established oncogenic factor in hepatocellular carcinoma and recently indicated in colorectal cancer." (PMID 28241877, 2017). "Activation of YAP1 has been correlated with poor prognosis for colorectal cancer and poor response to cetuximab." (PMID 29340043, 2017). "YAP1 activation correlates with colorectal cancer progression and poor prognosis [192, 435‐438]." (PMID 40066231, 2025). "USP47 enhances YAP1 stability in colorectal cancer and correlates with poor prognosis, whereas circRNAs and m6A modifications, particularly those mediated by METTL3—orchestrate YAP1 expression in hepatocellular carcinoma to drive vasculogenic mimicry and drug resistance." (PMID 40977060, 2025). "Interestingly, Yap1 can also regulate actin organisation, as shown in gastric or colorectal cancer cells, where Yap1 impairs both cytoplasmic G-actin and F-actin dynamics." (PMID 39927755, 2025). "In colorectal cancer, METTL3 promotes the expression of circ1662 by m6A modification of circ1662 through binding to its flanking strand, while circ1662 can regulate SMAD3 expression by accelerating the nuclear localization of YAP1, which ultimately promotes invasive metastasis of colorectal cancer." (PMID 39289775, 2024). "Moreover, MIR4435-2HG, by reducing miR-206 and miR-125b-5p and upregulating Yes-associated protein 1 (YAP1) and Semaphorins 4D (Sema4D), promotes proliferation, migration, invasion, and EMT of colorectal cancer cells." (PMID 37998733, 2023). "The expression of BIRC5 is up-regulated by the YAP1 in esophageal and colorectal cancer." (PMID 36768755, 2023).
colorectal cancer (continued). "Another study also showed that miR-103a-3p knockdown suppressed HIF1A expression by targeting the core molecules LATS2 and SAV1 of the Hippo/YAP1 pathway, contributing to reduced proliferation, invasion, migration, glycolysis and angiogenesis in colorectal cancer." (PMID 35094292, 2022). "Additionally, m6A-induced circ1662 was proven to promote colorectal cancer cell metastasis by promoting YAP1 nuclear localization." (PMID 36428672, 2022). "In addition to its oncogenic role, YAP1 participates in the YAP1/SIX2 pathway involved in the resistance toward anti-EGFR antibody cetuximab treatment in colorectal cancer." (PMID 35954483, 2022). "Besides, the expressions of YAP1 in cancer and normal tissues of four cancer types, including pancreatic cancer, glioma, ovarian cancer, and colorectal cancer were verified by GSE16515, GSE4290, GSE14407, and GSE24514." (PMID 35685435, 2022). "Based on the BioGRID database, it was demonstrated that MYL9 could bind to YAP1, which is a pro-cancer signaling pathway involved in colorectal cancer." (PMID 34974798, 2022). "Furthermore, DUSP10 is highly expressed in colorectal cancer (CRC) cell lines and promotes CRC cell proliferation via the regulator of yes-associated protein 1 (YAP1) activity." (PMID 36713584, 2022). "YAP1 was elevated in gastric cancer, cholangiocarcinoma, pancreatic cancer, and colorectal cancer." (PMID 35911146, 2022). "In addition, TCGA database analysis showed that YAP1 was overexpressed in gastric cancer, cholangiocarcinoma, and colorectal cancer." (PMID 35911146, 2022). "Similarly, miR-590-5p is proposed to be expressed at lower levels in colorectal cancer, and miR-590-5p upregulation restrains the tumor proliferation and metastasis by inhibiting YAP1." (PMID 35310934, 2022). "YAP1 signaling is a pro-cancer signaling pathway involved in the role of colorectal cancer." (PMID 34974798, 2022). "YAP1 has been reported as a target of miR-590-5p in colorectal cancer." (PMID 32066878, 2020). "Here, a Yes‐associated protein 1 (YAP1) target lncRNA LINC00152 is identified, and a critical role of YAP1/LINC00152/FSCN1 axis in the tumorigenesis of colorectal cancer (CRC) is revealed, which may provide a potential new target for CRC diagnosis and therapy." (PMID 32042551, 2020). "Long non-coding RNA ZEB1-AS1 silencing could inhibit cell proliferation and induce apoptosis of colorectal cancer via regulating miR-205 and YAP1." (PMID 32190742, 2020). "Moreover, another report indicates the β-catenin/TCF4 complex upregulates YAP1 expression in colorectal cancer (CRC) cells via binding to the promoter region of YAP1." (PMID 30934860, 2019). "Furthermore, nuclear localization and overexpression of YAP1 have been correlated with a poor prognosis in colorectal cancers and other cancer types." (PMID 31216773, 2019). "In addition, TIAM1, a component of the Wnt-regulated destruction complex, has recently been shown to antagonize TAZ and YAP1 in colorectal cancer cells by promoting TAZ cytoplasmic degradation and suppressing YAP1/TAZ interactions with TEADs." (PMID 29565815, 2018). "Initially, we quantified YAP1 protein levels in various ovarian and colorectal cancer cell lines." (PMID 28827520, 2017). "Most strikingly, YAP1 was found to be negatively correlated to miR-375 in CRC tissue samples indicating that targeting of YAP1 by miR-375 is also relevant for the tumorigenesis of colorectal cancer." (PMID 24892549, 2014). "AHR-mutants have increased susceptibility to colorectal cancer development and our work provides further mechanistic insight into the cancer protective functions of AHR in colonic epithelial cells by demonstrating a key role for AHR in restricting Yap1-mediated transcriptional activity." (PMID 35383166, 2022). "Importantly, KDM3A has been shown to upregulate YAP1 and the Hippo pathway in colorectal cancer." (PMID 33888871, 2022).
colorectal cancer (continued). "In colorectal cancer tissues, the downregulation of METTL14 resulted in reduced levels of miR-375, leading to the promotion of CRC growth and migration through the YAP1 and SP1 pathways, respectively." (PMID 40136363, 2025). "Paracrine signals from CAFs are also mediated by IGF2 as, in fact, exposure of colorectal cancer cells to CAF-derived IGF2 increases the activation of the IGF1R and downstream signaling, including the Hippo–YAP1 pathway." (PMID 38892104, 2024). "For therapeutic intervention, colorectal cancer organoid and in vivo studies demonstrated the benefit of co-targeting IGF1R and YAP1 with the anti-IGF1R tyrosine kinase inhibitor (TKI) picropodophyllin (PPP) and verteporfin (VP), a YAP1 inhibitor." (PMID 38892104, 2024). "Recent publications demonstrated that exogenous delivery of miR-15a and, specifically, 5-FU-miR-15a significantly reduced the expression levels of YAP1 and BCL2 in pancreatic and colorectal cancer cell lines, respectively, and led to growth inhibition." (PMID 36835366, 2023). "MALAT1 also increases the transcriptional activity of YAP1, which can alter the HR as well as the non–homologous end joining (NHEJ) pathway, to confer radioresistance to colorectal cancer cells." (PMID 37812088, 2023). "m6A circNSUN2 regulates cytoplasmic export and stabilizes HMGA2 to promote colorectal carcinoma (CRC) liver metastasis (LM); In colorectal cancer, another METTL3-induced circ1662 promoted CRC cell invasion and migration by accelerating YAP1 nuclear transport." (PMID 36861189, 2023). "By the analysis of DFS, we only found that the difference in YAP1 expression affects the median time of DFS in pancreatic cancer (MST: 371 vs. 542 days, P=0.026) and colorectal cancer (P=0.002)." (PMID 35911146, 2022). "Overexpression of YAP1 can induce epithelial-mesenchymal transition (EMT) and enhance cell migration and invasion in colorectal cancer cells." (PMID 35601153, 2022). "YAP1 can transactivate FSTL3, thereby forming a positive feedback loop that promotes EMT, aerobic glycolysis, and the invasion and metastasis of colorectal cancer cells." (PMID 36325361, 2022). "In addition to promoting metastasis, the DDX3X-induced YAP1/SIX2 axis might be responsible for resistance to treatment with the anti-EGFR antibody cetuximab (CTX) in colorectal cancer harbouring wild-type KRAS via enhanced autophagy and anti-apoptotic mechanisms." (PMID 33627125, 2021). "We observed that cell lines derived from human tumors with elevated YAP1 levels, such as PC3 (prostate cancer), COLO-320 and WiDR (colorectal cancer), displayed growth arrest to varying extents upon uptake of TONDU peptide." (PMID 32540914, 2020). "Here, a YAP1 target gene, long intergenic noncoding RNA 00152 (LINC00152), which is highly expressed in colorectal cancer (CRC), is identified." (PMID 32042551, 2020). "Zhong M's research found that the proton‐sensing receptor GPR4 is highly expressed in colorectal cancer, and GPR4 can promote the metastasis of colorectal cancer cells by inhibiting LATS activity and YAP1 nuclear translocation." (PMID 33090721, 2020). "In human colorectal cancer cells and tissues, MALAT1 expression positively correlates with YAP1, negatively correlates with miR-126-5p and miR-20b-5p expression, and predicts poor patient prognosis." (PMID 32174966, 2020). "miR-375 has been suggested to inhibit colorectal cancer growth by targeting the PI3K/Akt signaling pathway and reduce cell viability by targeting YAP1 to induce apoptosis." (PMID 27276676, 2016). "Through knocking down and overexpressing ENO2, another study demonstrated ENO2′s role in driving the metastasis of colorectal cancer (CRC) cells by activating the YAP1-induced EMT process but was independent of glycolysis regulation." (PMID 39061144, 2024).
colorectal cancer (continued). "In colorectal cancer (CRC), CNN2 was found to form a complex with YAP1 and EGR1, thus regulating EGR1 expression and promoting CRC, which could be considered as a potential therapeutic target for CRC." (PMID 37188478, 2023). "Additionally, S727 was phosphorylated by MAPK in embryonic stem cells, correlated with YAP1 in glioma and PIK3K-AKT-mTOR in colorectal cancer cells." (PMID 37388733, 2023). "To explore the clinical relevance of CXCR7 activation with expression of nuclear YAP1 and EMT markers in colorectal cancer patients, we collected 22 pairs of human CRC specimens and adjacent normal colonic tissues for immunohistochemistry, Western blot and RT-qPCR analysis." (PMID 36210463, 2022). "The YAP1 expression was not changed in liver cancer (P=0.376), but only gastric cancer, cholangiocarcinoma, and colorectal cancer had statistical differences." (PMID 35911146, 2022). "In colorectal cancer, MIR4435-2HG binds miR-206-3p to up-regulate downstream YAP1 expression." (PMID 35784328, 2022). "FGF8 was elevated in colorectal cancer tissues, and high FGF8 expression in colorectal cancer cells led to EMT marker expression, enhanced proliferation and invasion, and in vivo tumor growth and metastasis in a YAP1-dependent manner." (PMID 33801580, 2021). "In human colorectal cancer cells, MALAT1 expression is up-regulated by YAP1, sponges miR-126-5p and miR-20b-5p, and thereby up-regulates the expression of tumor cell stemness proteins such as Oct4 and Nanog and metastasis-associated molecules such as VEGF, SNAI2, and TWIST." (PMID 32174966, 2020). "miR-375 reverses chemoresistance by targeting YAP1 and SP1 in colorectal cancer." (PMID 32457613, 2020). "According to the results of the subgroup analysis, there were no clear relations between YAP1 with OS in non-Asians, colorectal cancer, lung cancer, renal cancer, and ovarian cancer." (PMID 31613226, 2019). "Moreover, the YAP1/six2 axis is required for DDX3-mediated tumor aggressiveness and cetuximab resistance in KRAS wild-type colorectal cancer." (PMID 30832689, 2019). "However, there are only two studies that analyzed the influence of YAP1 expression on PFS in ovarian cancer (OC) and colorectal cancer (CRC)." (PMID 29850494, 2018). "However, YAP1 expression was not significantly related to prognosis in breast, lung, gastric, esophageal, and colorectal cancer." (PMID 34150844, 2021). "Thus, Yap1 gene amplification appears to occur in mice under KRAS ablation in a KRAS G12D-dependent mouse pancreatic tumor model, while a genome-scale cDNA screen identified activation of YAP1 as a factor for survival upon KRAS knockdown in KRAS G13D mutant colorectal cancer cell lines." (PMID 34685695, 2021). "This revealed a very low to absent protein expression of YAP1 in OVCA432 ovarian cancer cell line in comparison to a panel of different ovarian and colorectal cancer cells." (PMID 28827520, 2017).
gastric cancer (127 papers, 2013 to 2026). A primary or metastatic malignant neoplasm involving the stomach. "Research indicates a strong association between H. pylori infection and the Hippo-YAP1 pathway in gastric cancer." (PMID 39809787, 2025). "Although these studies have been correlative, the present study, in which we use a hyperactive gp130 mutant (Gp130FF) gastric cancer mouse model, we demonstrate a causal relationship between gp130/IL-11 signalling and Yap1 function." (PMID 37957015, 2024). "The study shows that Yap1 expression correlates with poor outcomes in human gastric cancer and causally contributes to disease progression in mice via cancer cell–intrinsic and –extrinsic mechanisms." (PMID 37957015, 2024). "USP49 targets Yes-associated protein 1 (YAP1) for maintaining the stability of YAP1 in gastric cancer, leading to induction of cell proliferation, metastasis, chemoresistance." (PMID 37359559, 2023). "Striatin 3 upregulation resulted in hyperactivation of YAP1, leading to loss of Hippo tumor-suppressive functions, which ultimately correlated with poor prognosis in a cohort gastric cancer patients." (PMID 36328247, 2022). "To demonstrate that CIC is sufficient to suppress YAP1 expression, we rescued a loss-of-function CICF780S variant in AGS gastric cancer cells and observed a decrease in YAP1 expression." (PMID 36198276, 2022). "This study showed that METTL3 promoted the proliferation and metastasis of gastric cancer by modifying Yes-associated protein 1 (YAP1) mRNA m6A." (PMID 34394353, 2021). "Our current study further demonstrated that the expression of YAP1/TEADs and the AGK protein was highly associated and that YAP1/TEADs can transcriptionally up‐regulate AGK expression in gastric cancer cells." (PMID 32827244, 2020). "Hippo-Yes-associated protein 1 (YAP1) plays an important role in gastric cancer (GC) progression; however, its regulatory network remains unclear." (PMID 38493426, 2024). "MiR-15a and miR-16–1 could be considered diagnostic factors for gastric cancer, reducing YAP1 expression to inhibit the proliferation, monolayer colony formation, invasion, and migration of gastric adenocarcinoma cells." (PMID 35701841, 2022). "Given the facts that LATS1 is a critical regulator of YAP1 5 and YAP1 can upregulate Gli1 expression in esophageal squamous cell carcinoma 30 and gastric cancer 31, we speculated that YAP1 might be implicated in LATS1-mediated Gli1 suppression." (PMID 35003351, 2021). "Our current data indicate an association of AGK with YAP1 in gastric cancer; thus, we compared the expression of these proteins in 120 gastric cancer tissue samples and found that both YAP1 and AGK were significantly up‐regulated in tumour tissues, which is consistent with previous studies." (PMID 32827244, 2020). "Recent studies reported that YAP1 expression was associated with gastric cancer carcinogenesis and malignancy, which suggested that YAP1 could possibly be a potential treatment target for GC." (PMID 32647495, 2020). "Importantly, AGK expression was associated with the YAP1 expression in gastric cancer cells and tissues." (PMID 32827244, 2020). "Interestingly, we found that the AGK mRNA and protein levels were low in YAP1 deficient MKN‐45 cells, while YAP1‐expressing gastric cancer cell lines had higher AGK expression compared with GES‐1 cells." (PMID 32827244, 2020). "The Yes-associated protein (YAP1) is a main effector of the canonical Hippo pathway, which contributes greatly to tumor initiation, progression, and metastasis in multiple cancers, including gastric cancer (GC)." (PMID 33489890, 2020). "Likewise, activation of YAP1 was significantly associated with poor prognosis in ovarian cancer, liver cancer, and gastric cancers." (PMID 29340043, 2017).